IL6 (interleukin 6)
Diseases named in the same sentence as IL6 in open-access papers (continued):
Sharing a sentence is not in itself a finding about the gene and the disease.
infection (continued). "We evaluated the systemic and tissue parasitism, the survival and the body mass rate, the release of inflammatory mediators (TNF, IL-6, IL-15, CCL2 and creatine kinase) and the tissue inflammation at day 30 post-infection." (PMID 37505639, 2023). "In contrast, infection with IPTG-treated BL21/pEhaF resulted in a marked decrease in IFNβ, IL-6, and IL-1β demonstrating that in trans expression of EhaF is sufficient for the innate immune inhibition." (PMID 37041208, 2023). "Studies reported that serum TNFα was the first elevated cytokine due to LI infection, followed by the gradual increase in the secretion of IFN-γ and IL-6, while the serum concentrations of IL-10, IL-4, and TGFβ decreased." (PMID 37372164, 2023). "For molecular detection, CircZSWIM6 infection enhanced the expression of senescence markers p16 and p21, SASPs such as CXCL1 and IL‐6, decreasing aggrecan‐positive ECM components." (PMID 36604982, 2023). "Specifically, increased responses in IL-6, KC, and MCP-1 were evident at 72 hours post infection, which were then reversed at 96 hours post infection with i.n. exposure promoting the greater response." (PMID 37883420, 2023). "The infection is self-limiting as the subsequent production of gamma interferons IFN-γ, IL-1rs, IL-6, IL-8, and MCP-1 stops viral replication." (PMID 36932335, 2023). "The pro-inflammatory cytokines (Th1 immune response) (IL-1, IL-2, IL-6, IL-8, IL-18, IFN-γ, and TNF-α) generally regulate growth, cell activation, differentiation, and homing of the immune cells to the infection sites." (PMID 38133693, 2023). "ELISA results showed decreased levels of inflammatory cytokines IL-6, IL-1β, and TNF-α at each infection time point." (PMID 38076459, 2023). "Inflammatory cytokines, such as IL-1, IL-6, TNF-α, and IFN-γ, are the main mediators of immunological and pathological responses to stress and infection." (PMID 37756067, 2023). "The direct pathways include bacterial invasion and infection, and the indirect pathways include increases in C-Reactive protein (CRP) and interleukin-6 (IL-6)." (PMID 37239434, 2023). "This reduction was accompanied by a diminished immune response to infection, as indicated by the lowered levels of TNF-α, IL-6, and IL-10 and altered CD4+/CD8+ T-cell ratio." (PMID 38139181, 2023). "Expression of viral latent proteins after infection amplified the viral effects on p38 and MK2, but also on ZFP36L1, altogether resulting in a transitory and limited increase in IL-6 and TNFα transcription and release." (PMID 37830871, 2023). "IL-6 deficiency results in reduced Tfh differentiation and antibody-mediated immunity, a process in part dependent on IL-6 signaling on CD4 T cells to sustain Tfh formation and function at the later stages of infection." (PMID 37583704, 2023). "Some of the most relevant cytokines in this scenario are IL-6, IP-10, macrophage inflammatory protein 1α (MIP1α), MIP1β, and MCP1, all of which attract monocytes, macrophages, and T cells to the site of infection." (PMID 37175995, 2023). "In mice, R7 more effectively protected mice from infection with MDR E. coli or LPS and alleviated inflammation than its parental peptides by inhibiting the production of proinflammatory cytokines (TNF-α, IL-6, and IL-1β) and promoting IAP and IL-10." (PMID 37973936, 2023). "The results revealed that the release of IL-6 and TNF-α in sera following 2308ΔotnK and 2308ΔeryAΔotnK infection was significantly reduced relative to that found following infection with strain 2308." (PMID 37671873, 2023). "An array of cytokines, including Interleukins (IL), IL-12, IL-23, IL-6, IL-1, tumour-necrosis factor-alpha (TNF-α) and IFN-γ are released during infection and drive the immune response and containment of the infection." (PMID 38089636, 2023).
infection (continued). "IL-1β, IL-6, and TNF-α mRNA expressions were significantly induced 12 h after infection with B1033, and when complemented with fadD33, these mRNA expressions reverted to those observed in the wild-type BCG strain." (PMID 37998345, 2023). "To assess the immunological response of C57BL/6J- Cftrtm1UncTg(FABPhCFTR)1Jaw/J mice to S. maltophilia and P. aeruginosa polymicrobial infection, we measured inflammatory markers in the BALF by multiplex assay for IL-1α, IL-1β, IL-6 and TNF-α." (PMID 36748431, 2023). "Markers IL-1β, IL-6 and TNF-α also decreased following polymicrobial infection as compared to single-species P. aeruginosa infection, which was significantly higher than uninfected controls (****P<0.0001)." (PMID 36748431, 2023). "Another study using VARV-infected cynomolgus macaques reported cytokines such as IFN, IL-6, CCL4 (also recognized as MIP1), CCL2 (also identified as MCP1), and IL-8 were all elevated in the first 4 days after infection." (PMID 37533932, 2023). "The levels of IL-6 in both primary astrocytes and BV2 cells infected with S. suis strain P1/7 peaked at 24 h post-infection." (PMID 37111486, 2023). "We therefore sought to examine the role of IL-6, IL-17, and MCP-1 in the transition to a proinflammatory state in the lung during infection." (PMID 37338372, 2023). "The infection with Mtb increased the Fibroblast growth factor β (FGF-β), Interleukin (IL) 6 (IL-6), and Vascular endothelial growth factor (VEGF)." (PMID 37375056, 2023). "A considerable elevation in IL-6 and TNF-α indicated the mice’s evident systemic inflammatory response to the E. papillata-induced infection." (PMID 36875142, 2023). "The mRNA expression of pro-inflammatory cytokines, including IL-1β, IL-6 and TNF-α were significantly higher in the infection group than that in the control and nisin group (P < 0.05)." (PMID 37803465, 2023). "Of note, similar to TNF-α and IL-6, the quantity of IL-27 decreased when TLR-2 or TLR-4 were blocked prior to infection." (PMID 36863206, 2023). "Neutrophilia, low MHCII expression by monocytes, and elevated plasma Resistin, IL-6, myoglobin, and VCAM-1 correlated with fatal infections." (PMID 37598150, 2023). "The levels of mRNA expression of pro-inflammatory (IL-6 and IL-8) and anti-inflammatory (IL-10) cytokines, as well as of type I IFN (IFN-α/β) and type II IFN (IFN-γ), were measured at 24 h post-infection in single-infected and co-infected cells." (PMID 37243291, 2023). "Immunoglobulin (IgG) and cytokine (IL-1β, IL-6, IL-10, IFN-γ) levels were determined in ewes’ plasma collected before infection and at parturition, in lambs’ plasma at 24 and 72 h after their birth, and in colostrum samples at parturition and 72 h later." (PMID 37508158, 2023). "The results show that CATH-1 significantly reduced the secretion of IL-6 and TNF-α at 2 h post-infection (hpi) when CATH-1 was co-incubated with SS2." (PMID 37605242, 2023). "In general, infection and disease induce fever, a physiological defensive response mediated by cytokines, such as TNF-α, IL-1β, and IL-6." (PMID 37621534, 2023). "PSMB8 overexpression reduces the virus-induced activation of NF-κB promoters and suppresses the expression of proinflammatory IL-1β, TNF-α, IL6, IL8, and IFN-γ upon infection with nerve necrosis virus." (PMID 38031182, 2023). "The combination of both TMAO and CFT073 had significant additive effects on the release of IL-18R1 and synergistic effects on the release of IL-6, IL-24, IL-33, LIF, TGF-α, and LAP TGF-β1 compared to CFT073 infection alone." (PMID 37111409, 2023). "CD14+ monocyte-derived macrophages have an even more robust response to NDV infection, secreting high amounts of IFN, IL-6, IL-10 and TNF-α and producing toxic nitric oxide species even at low multiplicity of infection (MOI)." (PMID 37974615, 2023). "In this regard, we found that blocking TLR-2 or -4 prior to infection with M. tuberculosis decreased the production of TNF-α and IL-6." (PMID 36863206, 2023).
infection (continued). "Given the involvement of cytokines in the overall virulence of NDV, cytokines, particularly IL6 and IFN expressed during infection, are reviewed." (PMID 37112843, 2023). "Of note, the infection of Caco-2 cells with K. pneumoniae NTUH-K2044 strain induced levels of MCP-1, IL-8, IL-6, and TNF-α that were similar to those found in cells stimulated with LPS." (PMID 37240146, 2023). "Pro-inflammatory cytokines, such as IL-6 and TNF-α, help to initiate the inflammatory response necessary to control infection and prevent its systemic spread." (PMID 37662481, 2023). "The activation of TLRs and the subsequent cell signaling lead to the production of pro-inflammatory cytokines, including interleukin-6 (IL-6), interleukin-1 (IL-1), and tumor necrosis factor-alpha (TNF-α), which recruit immune cells to the site of infection." (PMID 37662905, 2023). "At 6 h post-infection, OMA- and NSC-treated cells had an inhibitory effect on IL-1β, IL-6 and IL-8, while BARM inhibited IL-6 and IL-8 levels." (PMID 36992362, 2023). "We found that ACO2 KD substantially increased the production of secreted IL6 and IL8, which was further elevated upon infection with S. aureus." (PMID 37349299, 2023). "Further, they can secrete IL-6, as well as CXCL1/CXCL2, within 3–4 hr following Staphylococcus aureus infection, contributing to the recruitment of neutrophils to the site of infection, thereby facilitating the speedy elimination of invading pathogens." (PMID 37128298, 2023). "By performing H&E staining and ELISA at 7 days post-infection (dpi), we found that Sept2fl/flLyz2-Cre mice showed more severe inflammation in the lungs and higher cytokine levels of TNF-α, IL-1β, IL-6 and IL-12 p40 in the BALF than control mice." (PMID 37978190, 2023). "At the early stage of infection (week 1-2), IFN-γ and IL-6 levels were lower in groups C and D than in groups A and B." (PMID 37051240, 2023). "miR146a-5p was predicted to be a negative regulator of B. burgdorferi-induced inflammation in early infection with mRNA targets including TLR2, STAT1, ICAM1, and IL6." (PMID 37319241, 2023). "TNF-α, IL-6, IL-8, IL-10, IL-13, and IL-33 in children with HRSV were significantly increased in severe infection compared to mild infection (p < 0.05) in children with HRSV." (PMID 37239461, 2023). "The previous review also focused on serum biomarkers, including IL-6, IL-8 and procalcitonin, which cannot differentiate UTI from other sources of infection." (PMID 36761839, 2023). "Another targeted transcriptomic study of PJI-associated periprosthetic tissues found elevated levels of granulocyte colony-stimulating factor (G-CSF), IL-1β, IL-6, IL-8, and CD40L at infection sites." (PMID 36830206, 2023). "Luminex analysis confirmed that remdesivir potently blocked SARS-CoV-2-induced cytokine release from ALI lung organoids at 48 hours post-infection, particularly evident for GCSF, IFNG, IL6, CXCL10, CCL2, and TNFA." (PMID 37205380, 2023). "TNF-α, IL-6, IL-8, IL-10, IL-13, and IL-33 in children with HRSV were significantly increased in severe infections compared to mild infections." (PMID 37239461, 2023). "By quantitative RT-PCR (qRT-PCR), we confirmed that IL-6, IL-1β, and MMP-8 mRNAs were commonly upregulated in the liver and small intestine after infection and were all suppressed by anti-TNF-α Ab treatment." (PMID 37939119, 2023). "Infection with SARS-CoV-2 triggered inflammation, and increased cytokines such as IL-6 promoted the synthesis of hepcidin and ferritin." (PMID 37303950, 2023). "Subsequently, other pro-inflammatory cytokine genes were also induced, such as IL-6 and CXCL8, TNFA, IL23, and GM-CSF, with distinct functions in the inflammatory response following infection." (PMID 37237836, 2023). "Consistent with the murine infection model results, vimentin in STEC contributed to the transcription of IL-6, TNF-α, and IL-8." (PMID 36717839, 2023).
infection (continued). "Lower age, PCR CT, IL-6, IL-8, and IL-17A and higher IL-16, EGF, and CCL-5 appeared to provide the best univariate class separation for recurrent infection (versus recurrence-free survival and death)." (PMID 36975808, 2023). "RTS11 cells pre-treated with CgPACAP-38 and infected with F. psychrophilum produced a significant up-regulation of IL-1β at day 3 after infection, while IL-6 and TNF-α were up-regulated from day 1 post-infection." (PMID 37887185, 2023). "At 3 d post-infection, the cytokines interferon gamma (IFN-γ), IL-6, MCP-1, and TNF-α were significantly reduced in TgΔLOXL1-infected mice, which prompted us to examine TgΔLOXL1 in IFN-γ KO mice." (PMID 37646522, 2023). "IAVTNF-α demonstrated significantly higher levels of IL-6, IL-1β, IL-8, IFN-γ, and TNF-α in comparison to IAVQUI after 24 h infection." (PMID 37163429, 2023). "When bacteria and other pathogens enter our body, macrophages secrete inflammatory mediators including NO, PGE2, and proinflammatory cytokines (IL-6, IL-1β, and TNF-α) that attract immune cells to the site of infection and activate cells to eliminate them." (PMID 37513335, 2023). "The level of IL-6, IFN-γ, and IL-8 in PCV3-inoculated groups reached a peak at 35 days of infection." (PMID 36766419, 2023). "Our analysis revealed that IL-6 can effectively detect illness, including EOS and mild infections, in children." (PMID 38255366, 2023). "Particularly, IL-6 and IL-10 in the GN-BSI group were significantly higher than those in the GP-BSI group within the first 24 h post-infection." (PMID 37986183, 2023). "We analyzed hLO culture supernatants for the presence of ten cytokines and chemokines commonly produced by epithelial cells in response to infection (TNF-α, IFN-α2a, IFN-β, IFN-λ1, IL-8, IL-1α, IL-1β, IL-6, IP-10, MCP-1)." (PMID 37883246, 2023). "After infection, pigeons showed upregulated expression of toll-like receptors (TLRs), such as TLR2, TLR3 and TLR15, together with interferon (IFN) gamma (IFNɣ) and IL-6, whereas IL-18 expression was found down- regulated." (PMID 37711609, 2023). "This is in line with a previous study that reported synergistic effects between organic acids in the prevention of intestinal inflammation by lowering the production of IL-6 and TNF-α after infection with enterohemorrhagic Escherichia coli in mice." (PMID 37007531, 2023). "We also evaluated the levels of four proinflammatory factors (TNF-α, IL-6, IL-1β and IFN-γ) in THP-1 macrophages preincubated with chloroquine (20 μM) or rapamycin (5 μM), followed by infection with Mel+ or Mel˗ S. globosa conidia to activate autophagy." (PMID 37141335, 2023). "Reduced expression of interferon-responsive genes, IL-6, IL-1, IL-1, CCL5, and TNF-, was evidence that TLR3 signaling was downregulated during a live MPOX infection." (PMID 37533932, 2023). "As expected, the IL-6 and TNF-α secretion induced by LPS were also significantly inhibited by CVB3 pre-infection." (PMID 37243164, 2023). "We detected differences in the expression levels of IL-6 and PIAS3 during C. burnetii-infection between bovine and human macrophages." (PMID 36793725, 2023). "Among the cytokines, IL-1β, IL-6, and IL-18 are known to be very important cytokines that respond to a PAK infection [36, -38]." (PMID 36788468, 2023). "IL-6 and TNF-α are classified as pro-inflammatory cytokines that neurons and other cells can discharge in reaction to stimuli such as injury, infection, or stress." (PMID 37987444, 2023). "In mouse melioidosis with neurological symptoms, pro-inflammatory cytokine levels of IL-6 and TNF-α were relatively high during early infection, but later the level of TNF-α was decreased." (PMID 38001928, 2023). "ELISA measurements indicated enhanced expression of CCL28, IL-1β, IL-6, and TNF-α following infection with Adv-CCL28, compared with Adv-Ctl." (PMID 36713846, 2023).
infection (continued). "Several TLRs, TLR3 and TLR9 can recognize viral nucleic acids or viral protein produced by PRRSV leading to release many cytokines, such as IL-6, TNF-α and IFN-γ at the early stage of infection." (PMID 37099541, 2023). "We found that PRV-infection induced significantly higher transcriptional levels of TNF-α, IL-1β and IL-6, and that DMY-treatment exhibited significantly lower mRNA levels of these cytokines." (PMID 36851415, 2023). "While IL-6, IRF4, IRF6, and CXCL2 were significantly unchanged, TNF-α was significantly elevated in the infection-derived EVs at both 48 h and 72 h when compared to the control-derived EVs (* p = 0.01 and * p = 0.02, respectively) (respectively)." (PMID 36979955, 2023). "On day 3, 7 and 14 after infection, serum levels of IgA and cytokines (IFN-γ, IL-4 and IL-6) were measured." (PMID 37943403, 2023). "IL6 and TNF-α are proinflammatory factors, and previous studies have revealed that IL6 and TNF-α levels are increased during infection or tissue damage, and their low expression levels are of great significance to DF wound healing." (PMID 36670362, 2023). "After infection with HSV-1, cGAMP and exogenous nucleic acid stimulations, lower Ifnb1 and Il6 mRNA expression was found in the Ufl1−/− peritoneal macrophages." (PMID 35871231, 2023). "Infection with KSHV induces high levels of pro-inflammatory cytokines, chemokines and angiogenic factors such as TNF, IL-1α, IL-1β, IL-6, CXCL8, IFN-γ, VEGF, COX-2 and GM-CSF." (PMID 36634147, 2023). "At 4 dpi after Omicron BA.2 infection, newly-weaned hamster showed around 10-fold increase of IFN-α, IL-6, and TNF-α, and 4-fold increase of IFN-γ and CXCL10 in brain." (PMID 37122119, 2023). "It has been previously reported that HSP90, together with IL6/STAT3 signaling, is essential for the progression of various diseases, infections, and cancers." (PMID 37099596, 2023). "The clinical improvements and radiological findings were also consistent with decreased levels of cytokines, such as IL-6, IL-10, TNF-α, and IFN-γ, along with improvement of inflammation and infection markers." (PMID 37041589, 2023). "The levels of IL-1β, IL-6 and IP-10 were significantly reduced in the spleens of STING KO mice at 7 and 14 days after intratracheal infection." (PMID 37261352, 2023). "ELISA of culture supernatants revealed that Kpn infection induced high levels of IL-6 and TNF-α secretion in MH-S cells at 2 h post infection: 17.09 and 14.40 pg/mL, respectively (p < 0.05)." (PMID 37958922, 2023). "IL-6, an inducer of ROS that we showed is important in promoting the killing of acapsular GAS, was produced at similar levels between all infections." (PMID 37874162, 2023). "However, the main factor contributing to the increasing concentrations of NGAL in the serum/plasma of patients with inflammation is the population of activated neutrophiles, the presence of which in the foci of infection may be induced, among others, by high concentrations of IL-6." (PMID 37509519, 2023). "The serum results showed that IL-6 and TNF-α significantly increased after CsA infection (p < 0.01)." (PMID 37764093, 2023). "In summary, our model shows elevated IL-1β, IL-6 and CXCL8 mRNA levels after 24 h infection with PA." (PMID 37432929, 2023). "Production of cytokines and cells of innate immunity: Neutrophils and macrophages are the main cells involved in the fight against the parasite, while IL-8, IL-6 and TNF-α are the most produced cytokines in response to this infection." (PMID 37125086, 2023). "Inflammatory cytokines such as IL-6, IL-17, TNF-α, and INF-γ were elevated in infected animals, supporting active infection." (PMID 37512931, 2023). "Particle counts of small HDL appear to be largely downstream of IL-6 signalling, which likely confound observed estimates between HDL measures and infection." (PMID 37814277, 2023).